ELMO1 (engulfment and cell motility 1)
Diseases named in the same sentence as ELMO1 in open-access papers (continued):
Sharing a sentence is not in itself a finding about the gene and the disease.
gastric cancer (4 papers, 2017 to 2023). A primary or metastatic malignant neoplasm involving the stomach. "Our findings suggest that promoter methylation of CLIP4, IRF4, ELMO1, and MSC, together with a GDMI > 4, is a useful molecular panel for gastric cancer risk stratification in endoscopic biopsies." (PMID 28418867, 2017). "We also observed a statistically significant association between gastric cancer diagnosis and promoter methylation of IRF4, ELMO1, CLIP4 and MSC, after adjusting for age and sex." (PMID 28418867, 2017). "Our findings suggest that IRF4, ELMO1, CLIP4 and MSC promoter methylation coupled with a GDMI>4 are useful molecular tools for gastric cancer risk stratification in endoscopic biopsies." (PMID 28418867, 2017). "The discovery of the deleterious effect of ELMO1 alterations in CD may provide a link in association to many gastrointestinal tumors, mainly esophageal and gastric cancer, which feature alterations of ELMO1 in up to 8%, and this gene has been proposed as a diagnostic or prognostic biomarker." (PMID 36833303, 2023). "Together these results suggest that promoter methylation of IRF4, ELMO1, CLIP4 and MSC may be part of a gastric cancer CpG island methylator phenotype (CIMP)." (PMID 28418867, 2017). "Moreover, ELMO1 alterations have been shown to play a role in HPV-related oropharyngeal squamous cell carcinoma, in metastatic spread of squamous cell carcinoma by means of TGFβ signaling, and epithelial-to-mesenchymal transition in gastric cancer." (PMID 36833303, 2023). "Promoter methylation of IRF4 (p < 0.0001), ELMO1 (p < 0.0001), CLIP4 (p < 0.0001), and MSC (p < 0.0001), is also associated with increasing severity from gastritis with no metaplasia to gastritis with metaplasia and gastric cancer." (PMID 28418867, 2017). "The promoter methylation of IRF4, ELMO1, CLIP4, and MSC is related with increasing seriousness from gastritis with no metaplasia to gastritis with metaplasia and gastric cancer." (PMID 33575272, 2020).
glioblastoma (4 papers, 2015 to 2020). The most malignant astrocytic tumor (WHO grade IV). "Methylation markers on ELMO1 were reported to be associated with cancers such as oropharyngeal squamous cell carcinoma and glioblastoma." (PMID 31340858, 2019). "Among 121 included glioblastoma patients, successful pyrosequencing results were obtained from 113, 104, and 119 of the patient samples for ELMO1, ELMO2, and ELMO3, respectively." (PMID 29495584, 2018). "In glioblastoma, ELMO1 has been shown to be specifically abundant in invasive areas of the tumors and to be central for promoting cell migration and invasion via activation of RAC1." (PMID 29495584, 2018). "Recent research has also confirmed that ELMO1 presents abnormal methylated status in glioblastoma." (PMID 32528944, 2020). "We found that the methylation levels of ELMO1 and ELMO2 were generally low, whereas ELMO3 methylation levels were high, in the glioblastoma samples." (PMID 29495584, 2018). "Together, these observations indicate a crucial role of the Graf (ARHGAP26)/Rac1/Cdc42 axis, not DOCK180 or ELMO1, in CD151-α3 integrin complex-mediated signaling in glioblastoma." (PMID 26377974, 2015).
hepatocellular carcinoma (4 papers, 2020 to 2023). A malignant tumor that arises from hepatocytes. "Overexpression of ELMO1 has a significant influence on cancer cell migration and invasion in the current study of hepatocellular carcinoma." (PMID 37251542, 2023). "ELMO1 encodes a member of the engulfment and cell motility protein family and has been previously linked to T2DM, hepatocellular carcinoma and inflammatory arthritis." (PMID 33933144, 2021). "Other studies have demonstrated that the overexpression of ELMO1 promotes cell motility and invasion in hepatocellular carcinoma and serous ovarian cancer." (PMID 32292657, 2020).
type 2 diabetes (4 papers, 2015 to 2025). "Also, recently large African American cohorts with type 2 diabetes have suggested that SNPs locus in the 13th intron of the ELMO1 gene was detected to be associated with DN." (PMID 27761430, 2015). "Remarkably, ELMO1 expression remained unchanged within the kidney of patients suffering from type 2 diabetes, although the renal expressional pattern of ELMO1 was similar to that of nondiabetic patients." (PMID 27849017, 2016).
Hypertension (3 papers, 2016 to 2024). The presence of chronic increased pressure in the systemic arterial system. "This association strongly indicates that altered ELMO1 expression in the placental vasculature may contribute to PE-mediated placental vascular disorders, which eventually induce hypertension in PE cases." (PMID 39600942, 2024). "This study not only investigated whether the ELMO1 gene was related to DN susceptibility, but also investigated whether the interaction effect existed between this gene and some significant environmental factors, such as hypertension, alcohol drinking." (PMID 31798690, 2019).
osteoporosis (3 papers, 2021 to 2024). A condition of reduced bone mass, with decreased cortical thickness and a decrease in the number and size of the trabeculae of cancellous bone (but normal chemical composition), resulting in increased fracture incidence. "ELMO1 is a cytoplasmic bridging protein, and previous research has indicated that its deletion reduces osteoporosis in instances of OPG deficiency, ovariectomy, and inflammatory arthritis in mouse models." (PMID 39201575, 2024). "While OPG-deficient mice exhibited osteoporosis, mice double-deficient for Elmo1 and Opg (Elmo1−/−Opg−/−) showed significantly improved bone density at both 16 and 30 weeks of age." (PMID 34404802, 2021). "Based on these combined omics data sets, together with detailed observations in preclinical models of osteoporosis and arthritis, the authors concluded that ELMO1 functions as part of a signaling network that regulates osteoclast function and bone loss." (PMID 37410317, 2023). "To address the role of ELMO1 in bone pathology, we started by analyzing several in vivo mouse models of osteoporosis/bone erosion." (PMID 34404802, 2021).
ovarian carcinoma (3 papers, 2019 to 2024). A malignant neoplasm originating from the surface ovarian epithelium. "ELMO1 could help DOCK1 to regulate the migration ability of ovarian cancer cells." (PMID 38438882, 2024). "ELMO1 and DDR2 have been demonstrated to mediate ovarian cancer progression." (PMID 36059959, 2022).
Salmonella Infections (3 papers, 2021 to 2025). Infections with bacteria of the genus SALMONELLA. "Among the proteins involved in mitochondrial pathways, the mitochondrial fission protein DRP1 was significantly upregulated in ELMO1-depleted cells and ELMO1-KO mice intestine following Salmonella infection." (PMID 41250600, 2025). "Together, we report an extensive comparative proteome profile of ELMO1-regulated host proteome components following Salmonella infection." (PMID 41250600, 2025). "Proteome profiling identifies a link between the mitochondrial pathways and the host–microbial sensor ELMO1 following Salmonella infection." (PMID 41250600, 2025). "Comparative proteome analysis of control and ELMO1-depleted murine J774 macrophages after Salmonella infection quantified more than 7000 proteins with a notable enrichment in mitochondrial-related proteins." (PMID 41250600, 2025). "Here, we have used TMT-guided LC-MS3 proteomics to determine the global quantification of proteins regulated by ELMO1 in macrophages during Salmonella infection." (PMID 41250600, 2025). "Here, we performed liquid chromatography multinotch MS3-tandem mass tag (TMT) multiplexed proteomics to determine the global quantification of proteins regulated by ELMO1 in macrophages after Salmonella infection." (PMID 41250600, 2025). "Seahorse analysis showed that Salmonella infection alters mitochondrial metabolism from oxidative phosphorylation to glycolysis-a shift significantly influenced by the depletion of ELMO1." (PMID 41250600, 2025). "The upregulation of proteins involved in mitochondrial fission and biogenesis in ELMO1-depleted macrophages after Salmonella infection suggests a putative role for ELMO1 in controlling mitophagy and other apoptotic pathways critical for mitochondrial health." (PMID 41250600, 2025). "Furthermore, ELMO1 depletion decreased the ATP rate index following Salmonella infection, indicating its importance in counteracting the effects of Salmonella on immunometabolism." (PMID 41250600, 2025). "In the current work, we identified BOLA1 as one of the major downregulated mitochondrial proteins and DRP1 as one of the major upregulated mitochondrial proteins in the proteomic profiles of ELMO1-downregulated macrophages and in ELMO1 KO mice following Salmonella infection." (PMID 41250600, 2025). "To understand the ELMO1-regulated host pathways, we have performed liquid chromatography Multinotch MS3-Tandem Mass Tag (TMT) multiplexed proteomics to determine the global quantification of proteins regulated by ELMO1 in macrophages during Salmonella infection." (PMID 41250600, 2025). "Further investigations are needed to determine whether the changes after Salmonella infection are all ELMO1-dependent or ELMO1-independent." (PMID 41250600, 2025). "Collectively, these findings showed that ELMO1, NOD2, and their interaction are important in bacterial clearance and pathogenesis during AIEC-LF82 and Salmonella infection." (PMID 36694274, 2023). "We also demonstrated that the absence of ELMO1 after Salmonella infection reduced ATP production and mitochondrial respiration." (PMID 41250600, 2025). "As observed for AIEC-LF82, in case of Salmonella infection the absence of either ELMO1 or NOD2 or both resulted in a delayed bacterial clearance and significant decline in levels of IL-6 and IL-1β compared to C1 cells." (PMID 36694274, 2023). "The result of the present study reveals that NOD2 and ELMO1 can interact with each other directly and can influence the course of bacterial infection by regulating bacterial survival/clearance, ROS generation and immune response during AIEC-LF82 and Salmonella infection." (PMID 36694274, 2023).
type 1 diabetes (3 papers, 2018 to 2023). "In a study of advanced DKD, defined as the presence of persistent proteinuria or ESRD, 284 DKD patients with proteinuria and 536 patients with DKD-ESRD were analysed for association of 359,193 SNPs, 106 in ELMO1, versus 885 type 1 diabetes mellitus (T1DM) controls." (PMID 30359254, 2018). "For example, among the strongest associations with the lead SNPs at the following loci include: CLEC16A, CD28, MICA, and ELMO1 with eosinophil counts; AHI1 with monocyte and neutrophil counts, asthma, and hay fever (also shared by CD28); and MICA with type 1 diabetes." (PMID 37120605, 2023).
ankylosing spondylitis (2 papers, 2021 to 2023). An autoimmune chronic inflammatory disorder characterized by inflammation in the vertebral joints of the spine and sacroiliac joints. "METTL14-mediated m6A modification of the ELMO1 3’UTR has been shown to enhance directional migration and osteogenic differentiation of MSCs, thereby improving the therapeutic efficacy in ankylosing spondylitis." (PMID 37865637, 2023).
cardiomyopathy (2 papers, 2021 to 2025). A disease of the heart muscle or myocardium proper. "To what extent the high expression of ELMO1 contributes to the B12 effects we observed is currently unknown, yet we observed a similar cardioprotective effect of B12 even in the Elmo1+/+Ins2Akita/+ mice having normal expression of ELMO1 and less severe cardiomyopathy than Elmo1H/HIns2Akita/+ mice." (PMID 34163008, 2021). "Our previous work confirmed the validity of the Rac1–NADPH oxidase pathway in ELMO1-driven ROS production, as oral inhibition of Rac (EHT1864) or Nox4 each partially mitigated cardiomyopathy, while pan-NADPH oxidase inhibition (VAS3947) markedly prevented it." (PMID 41300434, 2025).
diabetic cardiomyopathy (2 papers, 2021 to 2025). Diabetic cardiomyopathy is a disorder of the heart muscle in people with diabetes. "We previously demonstrated that oral high-dose B12 supplement mitigates diabetic cardiomyopathy in Akita diabetic mice expressing twice the normal levels of Elmo1 (Engulfment and cell motility 1)." (PMID 41463345, 2025). "B12 prevents and reverses the development of diabetic cardiomyopathy in the ELMO1 hypermorphic Akita mice, at least via direct scavenging of superoxide and the retrieval of IGF-1 signaling via modulating the SAMe-DNMT-SOCS1/3 cascade." (PMID 34163008, 2021).
gastritis (2 papers, 2017 to 2020). Inflammation of the stomach. "Using logistic regression, we observed a statistically significant association between gastritis patients with metaplasia > = 10% and promoter methylation of IRF4, ELMO1 and MSC, after adjusting for age and sex." (PMID 28418867, 2017). "Promoter methylation of IRF4 (p < 0.001), ELMO1 (p < 0.001), CLIP4 (p < 0.001), and MSC (p < 0.001), is strongly associated with increasing severity of disease in the histological progression from gastritis with no metaplasia, to gastritis with metaplasia, to gastric adenocarcinoma." (PMID 28418867, 2017).
glomerulosclerosis (2 papers, 2019 to 2021). A hardening of the kidney glomerulus caused by scarring of the blood vessels. "Overexpression of ELMO1 may result in the progression of glomerulosclerosis and occurred in cultured cells present in a high glucose environment." (PMID 33976959, 2021). "SNP rs741301 increases the production of ELMO1 which promotes phagocytosis, with excessive production of extracellular protein (type 1 collagen and fibronectin), and diminishes cell adherence, thereby causing the development and progression of T2DM glomerulosclerosis." (PMID 30713847, 2019).
inflammatory bowel disease (2 papers, 2023 to 2025). A spectrum of small and large bowel inflammatory diseases of unknown etiology. "Studies from our group have revealed that ELMO1 is involved in the sensing of microbes associated with Inflammatory Bowel Disease (IBD) and pro-inflammatory cytokines secretion." (PMID 36694274, 2023).
leukemia (2 papers, 2014 to 2017). A malignant (clonal) hematologic disorder, involving hematopoietic stem cells and characterized by the presence of primitive or atypical myeloid or lymphoid cells in the bone marrow and the blood. "Further studies using in vivo leukemia models are necessary to assess whether ELMO1 depletion could affect LSC homing and long-term engraftment, and ultimately whether targeting ELMO1 might have therapeutic benefit in the treatment of leukemia patients." (PMID 25360637, 2014). "This was consistent with previous study in which knock down of ELMO1, the partner gene of DOCK1, resulted in reduced chemotaxis of leukemia cells." (PMID 29069784, 2017).
adenoma (1 paper, 2013). A neoplasm arising from the epithelium. "We confirmed that ELMO1, EMCN, ITIH5, KCNAB1, and SLCO2A1 were downregulated in follicular carcinoma compared to adenoma." (PMID 24099521, 2013).
atherosclerosis (1 paper, 2021). A disease characterized by the build-up of fatty material and calcium deposition in the arterial wall resulting in partial or complete occlusion of the arterial lumen. "For instance, some proteins related to atherosclerosis were down-regulated in SF, such as ARG2, CD14, CD44, engulfment, and cell motility protein 1 (ELMO1), neutrophil gelatinase-associated lipocalin (LCN2), MPO, S100A8, or S100A9." (PMID 34572333, 2021).
colitis (1 paper, 2020). Inflammation of the colon. "In dextran sulphate sodium (DSS) experimental mouse model of colitis, systemic delivery of ELMO1- lentiviral vectors attenuated colonic inflammation and promoted recovery from colonic injury via Rac1 activation." (PMID 32178475, 2020).
COVID-19 (1 paper, 2025). A disease caused by infection with severe acute respiratory syndrome coronavirus 2. "By 6 weeks post-inclusion (T2), COVID-19 hypermethylation of genes with lowest p-value included NXN, FMNL2, ZBTB46, SLC35F3, and SHQ1, and the hypomethylated genes included ELMO1, XBP1, GRIK1, TNFAIP8, and SH3BP5." (PMID 41227320, 2025).
endometrial cancer (1 paper, 2022). Primary or metastatic malignant neoplasm involving the endometrium (mucous membrane that lines the endometrial cavity). "Also, VEGF signaling pathway, viral myocarditis, and PPAR signaling pathway were enriched in the high ELMO1 level, while base excision repair, homologous recombination, endometrial cancer, oocyte meiosis, cell cycle, and O-glycan biosynthesis were enriched in the low ELMO1 level." (PMID 36059959, 2022).
endometriosis (1 paper, 2022). The growth of functional endometrial tissue in anatomic sites outside the uterine body. "The AUCs (95%CI) of AQP1, BGN, DDR2, and ELMO1 were 0.96 (1.00–0.89), 0.98 (1.00–0.95), 1.00 (1.00–0.99), and 0.99 (1.00–0.98), respectively, demonstrating that each characteristic gene enabled to diagnose endometriosis accurately and sensitively." (PMID 36059959, 2022). "Through Lasso algorithm, four characteristic genes were determined among the shared endometriosis-related genes, containing BGN, AQP1, ELMO1, and DDR2." (PMID 36059959, 2022). "Altogether, our research determined four characteristic genes (BGN, AQP1, ELMO1, and DDR2) with the favorable efficacy in diagnosing endometriosis." (PMID 36059959, 2022). "Through the Lasso approach, we determined four characteristic genes among endometriosis-related genes, containing BGN, AQP1, ELMO1 and DDR2." (PMID 36059959, 2022). "In the two datasets, higher levels of BGN, AQP1, ELMO1, and DDR2 were confirmed in endometriosis than normal endometrium tissues." (PMID 36059959, 2022).
epilepsy (1 paper, 2017). A brain disorder characterized by episodes of abnormally increased neuronal discharge resulting in transient episodes of sensory or motor neurological dysfunction, or psychic dysfunction. "Instead, our findings suggest that mTORC1 inhibition may affect development of epilepsy, by modulating expression of specific subset of genes, including Elmo1, and point to a potential role for Elmo1 in morphological changes that accompany epileptogenesis." (PMID 26993296, 2017). "Nonetheless, however, the role of Rho-family small GTPases and actin reorganization in epilepsy is poorly understood and the role of Elmo1 in epilepsy has not yet been elucidated." (PMID 26993296, 2017).
hyperglycaemia (1 paper, 2016). "To evaluate hyperglycaemia and ELMO1 knockout effects on renal functionality, we assessed pronephric ultrafiltration." (PMID 27849017, 2016). "We found that, in the zebrafish pronephros, ELMO1 protects the glomerulus from apoptosis and from hyperglycaemia induced damage." (PMID 27849017, 2016). "In accordance with the GWAS indication, we have established that overexpression of ELMO1 actually helps to protect renal structure from pathogenesis under hyperglycaemia." (PMID 27849017, 2016). "Similar to hyperglycaemia induced changes, ELMO1 crispants exhibited alterations in the zebrafish pronephric structure." (PMID 27849017, 2016). "Subsequently, we collected pronephric cells from the Tg(wt1b:EGFP) zebrafish line subjected to hyperglycaemia and performed a real-time quantitative PCR, to assess expressional changes of ELMO1 within the renal system of the zebrafish embryo under normo- and hyperglycaemic conditions." (PMID 27849017, 2016). "Thus, it is further established that, even at a subcellular level, hyperglycaemia and ELMO1 CRISPR injections lead to podocyte structural adversities." (PMID 27849017, 2016). "However, hyperglycaemia leads to pathophysiological and functional alterations within the pronephros, which could be rescued via ELMO1 overexpression." (PMID 27849017, 2016). "In zebrafish, hyperglycaemia did not alter renal ELMO1 expression." (PMID 27849017, 2016).